EGFR (epidermal growth factor receptor)
Diseases named in the same sentence as EGFR in open-access papers (continued):
Sharing a sentence is not in itself a finding about the gene and the disease.
lung cancer (continued). "For example, if an article is about testing an epidermal growth factor receptor (EGFR) antagonist in lung cancer, one should report all associations with entities pursuing diagnostic or therapeutic strategies in cancer in general”." (PMID 31861770, 2019). "Toward repurposing drugs for CSC inhibition, we initially screened an NCI Diversity library of FDA-approved drugs using H460 human lung cancer cell line which contains mutations in the clinically relevant genes EGFR and KRAS." (PMID 31796785, 2019). "A novel EGFR-tyrosine kinase inhibitor (TKI), osimertinib, has marked efficacy in patients with EGFR-mutated lung cancer." (PMID 30651547, 2019). "Prominent examples include EGFR mutations in lung cancer and JAK2 mutations in myeloproliferative disorders." (PMID 31181801, 2019). "Accordingly, monitoring of de novo and acquired nucleotide mutations is essential for clinical treatment of lung cancers with EGFR-TKIs." (PMID 31426517, 2019). "It has been reported that the pro-apoptotic BCL-2 family member BIM is responsible for EGFR-TKI–induced apoptosis in lung cancers harboring oncogenic EGFR mutations." (PMID 31262325, 2019). "In mouse models of lung cancer driven by L858R/T790M and L858R/T790M/C797S EGFR mutations, the tumour shrinks when treated synergistically with EAI045 and cetuximab, suggesting that EAI045 and cetuximab exhibit mechanistic synergy." (PMID 31739412, 2019). "Tyrosine kinase inhibitors (TKIs) can significantly prolong overall survival for patients with advanced non‐small cell lung cancer (NSCLC) harboring epidermal growth factor receptor (EGFR)‐mutation or anaplastic lymphoma kinase (ALK)‐rearrangement." (PMID 31144459, 2019). "FAM83A, originally identified as BJ-TSA-9, is overexpressed in lung cancer and breast cancer tumors, and it is associated with breast cancer refractoriness to EGFR-TKI (tyrosine kinase inhibitors)." (PMID 30881348, 2019). "Although EGFRvIII is somewhat inhibited by erlotinib, this GBM-associated mutation is less sensitive to erlotinib than the EGFR kinase domain mutations found in lung cancer." (PMID 30267146, 2019). "This approach is exemplified in NSCLC, a group of histological diverse subtypes found in more than 80% of all lung cancer patients, in which tumour-driving EGFR mutations occur in approximately 10–20% of cases." (PMID 30959819, 2019). "Other studies were also performed on genetic factors of lung cancer in Martinique; 157 patients were studied in Martinique and very high levels of EGFR mutation were found, contrary to what is found in in Metropolitan France or in African Americans." (PMID 30876409, 2019). "In targeted therapy, gefitinib and erlotinib, EGFR inhibitors, were approved for the treatment of cancers with EGFR mutations or hyperactivation, including certain breast and lung cancers." (PMID 31179925, 2019). "In lung cancer, targeted gene assays are used for detecting EGFR variants in NSCLC with a reported concordance between tissue and plasma of 70% to 90%." (PMID 31818027, 2019). "Some prototypical examples include KRAS, NRAS, and BRAF mutations in colorectal cancers or secondary EGFR mutations in lung cancer against anti‐ EGFR targeted therapies." (PMID 30304546, 2019). "Our results confirm previous reports that EGFR mutations are more prevalent than KRAS in Chinese lung cancer patients." (PMID 31369215, 2019). "We aim to investigate the characteristic of brain magnetic resonance (MR) imaging and the association with the treatment response of epidermal growth factor receptor-tyrosine kinase inhibitors (EGFR-TKIs) for lung cancer with BM." (PMID 31415376, 2019). "The second most frequent level 2 results encompassed atypical activating EGFR mutations in lung cancer patients, supporting use of EGFR inhibitors for certain alterations." (PMID 30658646, 2019).
lung cancer (continued). "In a panel of EGFR-mutated lung cancer cell lines, mTOR inhibitors significantly suppressed glycolysis and down regulation of GLUT1 by RNAi reduced cell proliferation." (PMID 30970654, 2019). "In the present study, we characterized selected EGFR variants previously observed in lung cancer patients and expressed in a murine bone marrow pro‐B Ba/F3 cell model." (PMID 31314158, 2019). "Over 50% of the EGFR evidence items are associated with lung cancer or non-small cell lung carcinoma (NSCLC)." (PMID 31796060, 2019). "Previous studies have shown some possible yet conflicting links between family history of cancer and EGFR mutation in lung cancer." (PMID 31703574, 2019). "We summarized the potential CPGs and mutated sites reported in familial lung cancers where somatic EGFR mutation status was available." (PMID 31703574, 2019). "Treatment with selective early-generation epidermal growth factor receptor (EGFR) tyrosine kinase inhibitors (TKIs) has demonstrated high efficacy in patients with lung cancer harboring activating EGFR mutations." (PMID 32914023, 2019). "Of note, inhibition of the PI3K/AKT/mTOR pathway in lung cancer cells harboring EGFR mutations affects the glycolytic flux impairing their viability." (PMID 29124875, 2018). "Both in lung cancer and in GBMs, EGFR mutations are driver mutations and the tumors remain dependent on this oncogene for growth." (PMID 30518123, 2018). "On average, there are more than 300 mutations in each lung cancer, but only a few of these genes can promote or “drive” the lung tumorigenesis, mainly including EGFR_(epidermal growth factor receptor), ALK_(anaplastic lymphoma kinase), c-met and so on." (PMID 30217217, 2018). "Targeted therapy with tyrosine‐kinase inhibitors (TKI) including gefitinib has dramatically improved the rates of response and survival in advanced epidermal growth factor receptor (EGFR)‐mutated non‐small cell lung cancer (NSCLC)." (PMID 29664235, 2018). "In this study, we examined the association between EGFR gene polymorphisms and lung cancer risk among the Jordanian population." (PMID 30011810, 2018). "A number of studies have reported that the activation of JAK2/STAT3 signaling pathway induces acquired ELTN resistance in lung cancer cells harboring EGFR mutation." (PMID 30483119, 2018). "These tumors are characterized by a mutational MS3 signature that is associated with inflammatory tumor infiltrating B lymphocytes: as a consequence, the frequency of EGFR mutations is very high among lung cancers with a MS3 signature." (PMID 30060526, 2018). "The procedure can be used to identify a broad range of mutations, including KRAS, BRAF, and EGFR mutations, in patients with colon carcinoma, breast cancer, melanoma, and lung cancer." (PMID 29728089, 2018). "In the present studies, the results unveiled that the expression of phospho-EGFR was dose-dependently inhibited by propolin C in EGFR-mutated HCC827 lung cancer cells." (PMID 29681982, 2018). "Tyrosine kinase inhibitors (TKIs)-treatments bring significant benefit for patients harboring epidermal growth factor receptor (EGFR) mutations, especially for those with lung cancer." (PMID 29455669, 2018). "Hepatocyte growth factor (HGF) overexpression is an important mechanism in acquired epidermal growth factor receptor (EGFR) kinase inhibitor gefitinib resistance in lung cancers with EGFR activating mutations." (PMID 29664235, 2018). "Despite the efficacy of first- and second-generation EGFR-TKIs in the treatment of BM in lung cancer patients with EGFR mutations, the disease continues to progress after a short period of time." (PMID 29435193, 2018). "It has been well documented that EGFR mutations are very common in lung cancer patients of East Asian descent (up to 35%), so higher likelihood of testing among Asian patients was expected." (PMID 29554880, 2018).
lung cancer (continued). "The KRAS gene has a high mutation rate in patients with colorectal cancer and lung cancer, and confers the resistance to epidermal growth factor receptor (EGFR), tyrosine kinase inhibitors (TKIs), and EGFR monoclonal antibody agents." (PMID 30080912, 2018). "Gefitinib, a tyrosine kinase inhibitor, is used as a first line treatment against non‐small cell lung cancer (NSCLC) patients with EGFR activating mutations." (PMID 29901268, 2018). "For example, BCR-ABL plays a role in chronic myeloid leukemia, epidermal growth factor receptor (EGFR) in lung cancer, HER2 in breast cancer and the B-Raf mutation in melanoma." (PMID 30473665, 2018). "Long-term treatment of lung cancer patients with EGFR mutations with first-generation EGFR-TKIs results in the development of drug resistance and decreased treatment efficacy." (PMID 29435193, 2018). "In this report, we describe a novel oncogenic signaling pathway exclusively acting in mutated epidermal growth factor receptor (EGFR) non‐small cell lung cancer (NSCLC) with acquired tyrosine kinase inhibitor (TKI) resistance." (PMID 29449326, 2018). "Epidermal growth factor receptor (EGFR) mutation non-small cell lung cancer (NSCLC) is an important subtype of lung cancer." (PMID 29357971, 2018). "The phenomenon of lung cancer cells harbouring multiple EGFR mutations is worth mentioning, and it reportedly has accompanied the clinical use of first-generation small-molecule TKIs since 2004." (PMID 30055651, 2018). "For example, studies show that downregulated expression of miR‐17‐5p 9 and miR‐223 10 closely associated with EGFR‐TKI resistance in lung cancer, and overexpression of these miRNAs can overcome EGFR‐TKI resistance." (PMID 29493886, 2018). "There is a large difference in the EGFR gene mutation phenotype of lung cancer in China compared with that in Western countries." (PMID 30257820, 2018). "Second-generation TKIs: Afatinib is a dual EGFR/HER2 inhibitor that is now FDA-approved for the first-line treatment of lung cancers with EGFR L858R mutations or exon 19 deletions." (PMID 30337598, 2018). "EGFR signaling regulates the glucose metabolic pathway in EGFR-mutated lung cancer cells, and EGFR-TKIs decrease lactate production and glucose consumption." (PMID 29164298, 2018). "We found that activating EGFR mutations were predominantly detected in lung cancer, particularly in non-small cell lung cancer (NSCLC)." (PMID 29642553, 2018). "Lung cancer patients with an activating mutation in the EGFR (epidermal growth factor receptor) can develop resistance to erlotinib treatment, which is often mediated by the T790M resistance mutation in EGFR." (PMID 29448920, 2018). "Third-generation EGFR inhibitors such as rociletinib have been approved for treatment of EGFR-mutated non–small-cell lung cancer." (PMID 30134822, 2018). "The results revealed that inhibition of migration and invasion by propolin C was through downregulation of EGFR/PI3K/Akt and ERK-mediated EMT signaling pathways in EGFR-mutated HCC827 lung cancer cells." (PMID 29681982, 2018). "Epidermal growth factor receptor (EGFR) mutations are prevalent and well characterized in lung cancer and were shown by Gazdar (2009) to be associated with sensitivity and resistance to lung cancer treatment." (PMID 29464864, 2018). "The EGFR mutation rate of lung cancer in European and American countries is approximately 15%, whereas the probability of this mutation is 50% or more in China." (PMID 30257820, 2018). "The relationships between EGFR gene polymorphisms and the risk of lung cancer from previous studies are still controversial." (PMID 30011810, 2018). "EGFR tyrosine kinase inhibitors cause dramatic responses in EGFR-mutant lung cancer, but resistance universally develops." (PMID 30097569, 2018). "For example, smart searches like ‘melanoma cell lines with BRAF mutation’ or ‘lung cancer cell lines with high EGFR expression’ can be easily achieved by Boolean logic queries." (PMID 29726944, 2018).
lung cancer (continued). "Accumulating evidence from cancer genomics has revealed that EGFR is recurrently mutated in multiple cancer types, including lung cancer, glioblastoma, head and neck squamous cell carcinoma." (PMID 29976202, 2018). "CtDNA analysis has become established in specific settings, like the identification of T790M resistance-inducing mutations in epidermal growth factor receptor (EGFR)-mutated lung cancer." (PMID 29662530, 2018). "Alterations in the PI3K/AKT/MTOR pathway have been identified as driver mutations in primary NSCLC lung cancer but also to be known as the biomarkers of resistance to EGFR-tyrosine kinase inhibitors." (PMID 29899834, 2018). "Three patients were treated with imatinib, erlotinib, and vemurafenib on the basis of an Asp572Gly KIT mutation (lung cancer), an EGFR amplification (cervical cancer), and a Val600Glu BRAF mutation (colorectal cancer), respectively." (PMID 32914004, 2018). "Accumulating evidence from sequencing analyses has revealed the high frequency of EGFR mutations occurring in lung cancer, among which the exon 19 deletion appears to be the most prevalent one." (PMID 29976202, 2018). "A phase III study that included only EGFR-mutated lung cancer patients confirmed these observations." (PMID 30518123, 2018). "The new data indicate that serum carcinoembryonic antigen levels ≥ 2.12 ng/mL are associated with EGFR mutations, as previously observed in lung cancer." (PMID 29849818, 2018). "The identification of epidermal growth factor receptor (EGFR) activating mutations as targetable oncogene drivers produced a paradigm shift in the treatment of lung cancer, leading to a personalized approach according to the patients’ genomic profile." (PMID 30190486, 2018). "Mutations in EGFR that result in its constitutive activation are believed to be an important contributor to the tumorigenesis of many cancer types, including lung cancer." (PMID 29973561, 2018). "Non-small cell lung cancer (NSCLC) represents 85% of all lung cancers, with epidermal growth factor receptor (EGFR) mutations occurring in 10–30% of NSCLC patients." (PMID 30424034, 2018). "In lung cancer patients with loss of EGFR exon 19 with brain metastasis, 11C labeling as a positron emission tomography marker was used to show that erlotinib can pass through the BBB and enter the brain, facilitating observation of treatment efficacy." (PMID 29435193, 2018). "Lung cancer and pancreatic cancer often overexpress epidermal growth factor receptor (EGFR), which is associated with a worse prognosis." (PMID 30326853, 2018). "For lung cancer patients with EGFR-exon 19 deletions or an exon 21 Leu858Arg mutation, the standard first-line treatment is first-generation (gefitinib, erlotinib), or second-generation (afatinib) TKIs." (PMID 29455650, 2018). "Lung cancer is the leading cause of cancer-related death worldwide, and approximately 20% lung adenocarcinoma patients are epidermal growth factor receptor (EGFR) mutant." (PMID 30235778, 2018). "At our institution, EGFR mutational status is only tested in advanced-stage lung cancer with an adenocarcinoma component." (PMID 30458017, 2018). "We here describe a patient with EGFR mutation–positive lung cancer who developed disabling cerebral infarction due to Trousseau syndrome." (PMID 30034636, 2018). "Inhibitors of the epidermal growth factor receptor (EGFR) are important treatment options for non–small cell lung cancer (NSCLC) patients with activating EGFR mutations." (PMID 30588353, 2018). "For example, EGFR amplification was found to occur preferentially on the mutated allele in EGFR-mutant lung cancer." (PMID 29455648, 2018). "For instances, gefitinib and erlotinib which primarily inhibit EGFR, is used for EGFR-mutated lung cancer patients." (PMID 29455663, 2018). "Our studies propose a novel mechanism underlying the EGFR-promoted lung cancer cell migration that is mediated by NEDD4 through regulation of cathepsin B secretion." (PMID 29455656, 2018).
lung cancer (continued). "We have previously shown in EGFR-mutant lung cancer samples that VAF increased in association with shorter ccfDNA fragments." (PMID 30044795, 2018). "In the same line, EGFR-targeting TKIs are used in clinic to treat lung cancer displaying EGFR mutations." (PMID 29930749, 2018). "Combination usage of the epidermal growth factor receptor tyrosine kinase inhibitor (EGFR-TKI) has been more effective to the subset of lung cancer patients carrying L858 or exon 19 deletion EGFR mutations." (PMID 29463786, 2018). "Combination therapies with EGFR-TKIs and MEK inhibitor have been developed for lung cancers characterized by EGFR mutations (NCT02143466 and NCT02025114)." (PMID 29386539, 2018). "Within the lung cancer population, activated epidermal growth factor receptor (EGFR) mutations occur in 10% of Caucasians and 50% of Asians." (PMID 29696132, 2018). "Our study shows that treatment with naquotinib also induced in vitro MET amplification in lung cancers with EGFR mutations." (PMID 29386539, 2018). "In this study, we further probed the association between the EGFR wild type and EGFR exon 19 mutation, and established a scoring model for primary prediction to help first-step diagnosis of lung cancer." (PMID 30235778, 2018). "It is still controversial if the same discrepancy of EGFR mutations among ethnicities, which has been reported in lung cancer, exits in TNBC." (PMID 30007403, 2018). "Prior meta-analyses in lung cancer have shown decreased response to ICI in EGFR or ALK mutant subgroups, while BRAF mutations in melanoma have shown the opposite effect." (PMID 29743104, 2018). "EGF and the EGF receptor EGFR (HER1) have been extensively studied in cancer, with EGFR amplification implicated in the pathogenesis of lung cancer, glioblastoma, and breast cancer, among others." (PMID 30158935, 2018). "Paraffin-embedded tumour tissue specimens have conventionally been the main source of tumour material for EGFR mutation testing in lung cancer and they currently still account for the majority of diagnostic samples in the clinical practice." (PMID 29382302, 2018). "We now report a case of acute cerebral infarction due to Trousseau syndrome in a patient who was recently diagnosed with lung cancer positive for an activating EGFR mutation and who was subsequently treated safely with the EGFR-TKIs gefitinib and osimertinib." (PMID 30034636, 2018). "Somatic mutations in the gene encoding the epidermal growth factor receptor (EGFR) are detected in approximately 12% of non‐small cell lung cancers (NSCLCs) from Caucasian patients and in 30–40% of NSCLCs from Asian patients." (PMID 29212784, 2018). "Our study summarizes a single institutional experience of first-generation TKI therapy for lung cancers with compound EGFR mutations." (PMID 30055651, 2018). "EGFR rs712829, rs712830, rs2072454, and rs11543848 single nucleotide polymorphisms (SNPs) were genotyped to test for their association with lung cancer risk." (PMID 30011810, 2018). "It has been shown that lung cancer patients suffering from tumors with particular EGFR mutations survive longer, probably due to effective treatment." (PMID 29868480, 2018). "The T790M mutation in exon 20 occurs in ~60% of EGFR-mutated lung cancers that have developed acquired resistance to TKI therapy." (PMID 30337598, 2018). "It is well known that PD-L1 protein in lung cancer cells is induced by activation of EGFR signaling through both overexpression and mutation of EGFR." (PMID 30126206, 2018). "The clinical use of third-generation EGFR inhibitors is revealing the insurgence of novel mutations which confer to lung cancer cells the ability to escape EGFR inhibition." (PMID 29732058, 2018). "EGFR-mutated lung cancer cells with low expression levels of BIM exhibit low sensitivity to treatment with EGFR-TKIs." (PMID 30445769, 2018).